IL6 (interleukin 6)
Diseases named in the same sentence as IL6 in open-access papers (continued):
Sharing a sentence is not in itself a finding about the gene and the disease.
pancreatic cancer (continued). "As a result, NF-κB activation leads to upregulated expression of several pro-inflammatory cytokines in SCs, such as IL6, which in return promotes pancreatic cancer cell migration and spread in vivo and ex vivo." (PMID 32308766, 2020). "Soluble mediators like IL-6, IL-8, IL-1β, TGF-β, TNF-α, VEGF, SHH, etc. have been implicated in pancreatic cancer carcinogenesis." (PMID 32707920, 2020). "In other words, by means of the secreted IL-6, pancreatic cancer promotes the formation of a pro-metastatic niche in the liver." (PMID 32724299, 2020). "Treatment of pancreatic cancer cells with IL6 or conditioned media from PSC confirmed this in our in vitro experiment." (PMID 33177492, 2020). "CM from sh-Cav-1 PSCs exhibited upregulated levels of shh, MMP2, bFGF, and IL-6, which exert proliferative, invasive, angiogenic, and inflammatory functions during pancreatic cancer progression." (PMID 32377291, 2020). "Together, these results suggested an important role for SCs-derived IL6 in promoting pancreatic cancer cell migration, invasion, and EMT." (PMID 32308766, 2020). "M2 differentiation is induced by CAF-secreted molecules such as Chitinase 3 Like 1 (Chi3L1), C-X-C motif chemokine 12 (CXCL12) and interleukin 6 (IL-6) in breast, prostate and pancreatic cancers, respectively." (PMID 33066357, 2020). "In conclusion, our study shows that targeting the metabolic pathways affected by stromal IL6 can make pancreatic tumors amenable to checkpoint inhibitor therapy." (PMID 33177492, 2020). "We reveal that Cav-1-silenced PSCs facilitated the growth of pancreatic cancer cells via enhanced paracrine shh/MMP2/bFGF/IL-6 signaling." (PMID 32377291, 2020). "To determine this, we stimulated pancreatic cancer cells with IL6 in the presence of a STAT3 inhibitor Stattic." (PMID 33177492, 2020). "The proinflammatory cytokine IL-6, normally produced by macrophages and monocytes, is significantly increased in pancreatic cancer cells compared to normal cells of a healthy pancreas." (PMID 32850269, 2020). "Treatment with IL6 decreased mitochondrial complex 1 activity confirming that the pancreatic tumor cells were preferentially synthesizing lactate in the presence of IL6." (PMID 33177492, 2020). "IL-6 seems to play an important role in pancreatic cancer, with several studies indicating that high levels of IL-6 expression are associated with a significantly lower survival and a poor response to therapy." (PMID 33634030, 2020). "The authors demonstrated that IL-6 derived from fibroblasts in a primary pancreatic tumor binds to its receptor on hepatocytes, the main cell type in the liver, and drives the expression and activation of STAT3." (PMID 33322216, 2020). "Further, previous research has shown that inhibition of IL6 can sensitize pancreatic tumors to immune therapy." (PMID 33177492, 2020). "This is consistent with our findings that during the progression of pancreatic cancer, as the stromal develops and possibly differentiates into iCAFs and myCAFs, there is increased secretion of IL6." (PMID 33177492, 2020). "CAFs co-cultured with organoids derived from pancreatic cancer patients secrete IL-6, IL-11, and leukemia inhibitory factor (LIF), and these ligands activate a signal transducer and activator of transcription 3 (STAT3) in organoids." (PMID 33333727, 2020). "Pancreatic cancer cells stimulate the release of IL-8, IL-6 and interferon gamma-induced protein 10 (IP-10) from stromal cells and IL-8 induces skeletal muscle atrophy in vivo." (PMID 33291708, 2020). "Recent studies have explored IL-6 as a therapeutic target in pancreatic cancer; however, the available data are still limited." (PMID 32850269, 2020). "We show that the treatment of pancreatic tumors with anti-IL6 antibody results in tumor regression as well as decreased CD133 + population within the tumor." (PMID 33177492, 2020).
pancreatic cancer (continued). "Consistent with this, pretreatment of pancreatic cancer cells with IL6 also increased their resistance to gemcitabine and reduced apoptosis in these cells." (PMID 33177492, 2020). "Further, the stromal fibroblasts secrete IL6 as the major cytokine, which in turn, increases glycolysis in the pancreatic tumor cells, leading to increased lactate efflux in the microenvironment." (PMID 33177492, 2020). "Taken together, these results suggested a vital role for STAT3 signaling in SC-derived IL6-induced pancreatic cancer cell migration and invasion." (PMID 32308766, 2020). "Other researchers have reported that IL-32α can inhibit the JAK2/STAT3 signaling pathway and reverse the IL-6-induced EMT process in pancreatic cancer cells." (PMID 33097029, 2020). "IL6 inhibition has been shown to sensitize pancreatic tumors to immune checkpoint inhibitor therapy." (PMID 33177492, 2020). "Moses’s study has suggested that stimulated peripheral blood mononuclear cells from advanced pancreatic cancer patients usually produce high levels of IL-6." (PMID 32982584, 2020). "Our data additionally confirms that the treatment of pancreatic tumors with anti-IL6 antibody results in tumor regression as well as decreased CD133 + population within the tumor." (PMID 33177492, 2020). "Elevated CRP, IL6, IL8, and IL10, particularly in combination, are associated with an increase in pancreatic cancer morbidity and mortality." (PMID 31323984, 2019). "IL-6 expression of pancreatic cancer-educated macrophages was proven to be significantly increased using qRT-PCR and western blots, and IL-6 secreted by the macrophages cocultured with cancer cells increased markedly, as detected by ELISA." (PMID 31685825, 2019). "In pancreatic cancer, systemic levels of IL-1β and IL-6 showed a trend towards the development of future thrombosis." (PMID 31847343, 2019). "To gain further insight into the importance of IL-6 in macrophages as a key upstream factor driving CD59 up-regulation in pancreatic cancer cells, we neutralized IL-6 from the supernatants of the coculture system via a commercially available blocking antibody." (PMID 31685825, 2019). "The IL-6/IL-6R/JAK/STAT3 pathway has been implicated in the development of breast cancer, colorectal cancer, lung cancer (NSCLC), pancreatic cancer and skin cancers." (PMID 31101063, 2019). "For example, prominent IL-6 expression was detected in pancreatic tumor microenvironment, which is critical for tumor progression." (PMID 31640814, 2019). "We also demonstrated that IL-6 derived from pancreatic cancer-educated macrophages played vital roles in regulating the expression of CD59 in pancreatic cancer." (PMID 31685825, 2019). "IL-6 gene is strongly over-expressed in pancreatic cancer compared to normal tissues and IL-6 protein has strong cytoplasm expression in pancreatic tumor cells." (PMID 31150430, 2019). "Blockade of IL-6 with an antibody inhibits tumor growth and enhances survival in mice bearing aggressive pancreatic cancer cells." (PMID 31640814, 2019). "Experimental studies have shown that the IL6/GP130/STAT3 pathway is involved in pancreatic cancer tumorigenesis and progression as well as in the development of other tumors." (PMID 31139333, 2019). "During inflammation, cytokines and growth factors like TGF-ß1, PDGF, interleukin-1ß (IL-1ß), IL-6 and TNF-α are released in the pancreatic tumour microenvironment causing stimulation and activation of PSCs33." (PMID 30923340, 2019). "The combination of high CA 19.9 and high IL-6 identified pancreatic cancer patients with a very short median survival of only 7.5 months compared to 34.4 months for pancreatic cancer patients with normal levels of CA 19.9 and IL-6." (PMID 30038723, 2018). "Consistently, deletion of RAGE expression in pancreatic cancer cells leads to downregulated IL-6 expression, STAT3 localization to mitochondria, as well as the downregulation of the upstream signaling pathways such as phosphorylation of Jak1 and Src." (PMID 29474476, 2018).
pancreatic cancer (continued). "The area under the curve (AUC) for the diagnosis of pancreatic cancer was higher for CA 19.9 (AUC 0.94) compared to IL-6 (AUC 0.87)." (PMID 30038723, 2018). "The use of IL-6 as a therapeutic target is currently being investigated for pancreatic cancer, but trials should be done for the three other cancers types, especially since inhibition of anti-IL-6R with Tocilizumab seems to be well tolerated." (PMID 30038723, 2018). "Regarding pancreatic cancer, IL-6 protein expression in pancreatic cancer cells is significantly increased compared to normal pancreatic cells." (PMID 30038723, 2018). "Nine studies have assessed the use of IL-6 as a prognostic biomarker in patients with pancreatic cancer." (PMID 30038723, 2018). "Because of this limitation, we will evaluate the prognostic value of other common markers of systemic inflammation, including CRP and IL-6, in patients with pancreatic cancer and their correlation with serum LDH levels in future studies." (PMID 28345594, 2017). "Despite the inflammatory changes associated with chronic pancreatitis, the inflammatory markers CRP and IL-6 remain lower than stage II–IV pancreatic cancer patients." (PMID 28335509, 2017). "Recently, effects of the combination therapy using IL-6 Ab plus PD-L1 Ab in reducing pancreatic tumor size have been reported." (PMID 29113321, 2017). "A recent report showing that IL-6 inhibition of radiation -induced apoptosis in pancreatic cancer cells also supports our finding." (PMID 29113321, 2017). "Elevation of other serum proteins such as lactate dehydrogenase (LDH), C-reactive protein (CRP), and interleukin 6 (IL-6) also portends worse outcome of pancreatic cancer patients." (PMID 28335509, 2017). "For example, overexpression of IL-6 in a mouse pancreatic cancer model enhanced induction of Th17 cells." (PMID 27453801, 2016). "Our results are consistent with the recent data demonstrating that IL-6 is required for pancreatic cancer progression and emerges as a potential therapeutic target." (PMID 27177087, 2016). "IL-6 is over -expressed in most human pancreatic cancers and is synthesized and released by multiple cells in the tumor micro-environment, including tumor - associated macrophages, fibroblasts and pancreatic stellate cells." (PMID 27281617, 2016). "Taken together, these results demonstrate the role of IL-6 as a critical CAF-secreted factor responsible for CAF pro-tumor actions on pancreatic cancer cells." (PMID 27177087, 2016). "It is found that STAT3 forms a positive loop with two inflammatory cytokines IL-6 and IL-11 in pancreatic cancer: STAT3 directly affects the expression of IL-6 and IL-11, both of which are STAT3 activating cytokines." (PMID 26887043, 2016). "Our data provides important pre-clinical information and rationale for targeting IL-6/STAT3 signaling in pancreatic cancer." (PMID 27602757, 2016). "Conversely, Pim-1 and IL-6 mRNA and protein levels were increased in pancreatic cancer tissues as compared to normal tissues in four randomly selected paired samples." (PMID 26894969, 2016). "Among the soluble proteins that we found to be highly secreted by CAFs, IL-6 was identified as being a mediator of a significant proportion of CAF chemoprotective features in pancreatic cancer cells." (PMID 25834145, 2015). "Taken together, these results demonstrate the important role of CAF-secreted IL-6 in pancreatic cancer cell resistance to chemotherapies." (PMID 25834145, 2015). "We then assessed the status of IL-6 in pancreatic tumours in correlation with the presence of α-SMA-expressing CAFs." (PMID 25834145, 2015). "IL-6 functions in pancreatic tumor progression by activating the signal transducer and activator of transcription 3 (STAT3), as well as NF-κB in macrophages." (PMID 26404380, 2015). "Comparatively, PaSCs and pancreatic cancer Panc-1 and BxPC-3 cells expressed and secreted marginal amounts of IL-6 (< 0.1 ng/ml for 106 cells)." (PMID 25834145, 2015).
pancreatic cancer (continued). "This was supported by the observation that IFIT3 overexpression increases secretion of IL-6, which in turn favors pancreatic tumor growth and the maintenance of an inflammatory stimulus in the stromal tissue." (PMID 25650658, 2015). "Consistently, neutralizing IL-6 activity decreased CAF-CM-induced survivin expression in pancreatic cancer cells, whereas treatment of cancer cells with recombinant IL-6 increased it, mimicking CAF-CM effects (Fig6G–H)." (PMID 25834145, 2015). "The importance and functionality of CAF-secreted IL-6 on pancreatic cancer cell response to gemcitabine was evaluated." (PMID 25834145, 2015). "We found that, among all analyzed cytokines, only IL-6, IL-8, IL-10, and IL-23 levels significantly differed between patients with pancreatic cancer and other individuals." (PMID 24849506, 2014). "We found that there were higher levels of IL-6, IL-8, IL-10 and TNFα in patients with pancreatic cancer compared to healthy controls (for all, at least p<0.03)." (PMID 24849506, 2014). "Studies in a mouse pancreatic cancer model showed that tumor overexpression of IL-6 increases induction of Th17 cells, reduces development of cancer and improves mouse survival." (PMID 25419481, 2014). "Studies in a mouse pancreatic cancer model showed that implantation of tumor cells engineered to overexpress IL-6 results in induction of Th17 cells, reduced development of cancer and improved mouse survival." (PMID 25419481, 2014). "Overproduction of IL-6 and elevated APPR have been associated with decreased survival in patients with pancreatic cancer cachexia." (PMID 24624094, 2014). "To examine the invasion capacity of IL-6-treated pancreatic cancer cells, we performed an in vitro invasion assay using a transwell chamber coated with matrigel." (PMID 23922983, 2013). "To further confirm the correlation between EMT and the inflammatory tumor microenvironment, we evaluated the effects of IL-6 on pancreatic cancer cell EMT invitro." (PMID 23922983, 2013). "IL-6 is required for the maintenance and progression of pancreatic cancer precursor lesions, and thus is required for pancreatic cancer growth." (PMID 24474940, 2013). "CDF treatment remarkably decreased the production of hypoxia-induced VEGF and IL-6 in PC cells, suggesting an inhibitory role of CDF in the productions of hypoxia-induced VEGF and IL-6 in human pancreatic cancer cells." (PMID 23272057, 2012). "Cyclin E1, epithelial growth factor (EGF), IL-6, CXCL8, IL-10, and IL-1RA have all been shown to be elevated in individuals with pancreatic cancer and high IL-6 or IL-10 levels correlated to poor survival." (PMID 20214814, 2010). "IL-6 was shown to be expressed to high levels in numerous Ras-expressing cell lines including kidney, fibroblasts, human mammary epithelial cells and pancreatic cancer derived cell lines when grown in 2-D." (PMID 20929542, 2010). "In our study, we examined the effects of AG490 and IL-6 on growth capability of pancreatic cancer cells." (PMID 20482858, 2010). "In pancreatic cancer patients indeed increased levels of several cytokines such as IL-6, IL-18 and TNF-alpha can be found." (PMID 20961421, 2010). "The Jak inhibitor AG490 and interleukin-6 (IL-6) were added to the culture media of human pancreatic cancer cells SW1990 and Capan-2, respectively." (PMID 20482858, 2010). "Recent studies of pancreatic cancer reported that ZIP4 activates the IL-6/Stat3 pathway via CREB, leading to increased expression of neuropilin-1, vascular endothelial growth factor, and matrix metalloproteases." (PMID 20957146, 2010). "Previously, we have demonstrated that PBMC from weight-losing pancreatic cancer patients control the hepatic APPR by a primarily IL-6-dependent mechanism." (PMID 17088911, 2006). "At baseline, weight-losing pancreatic cancer patients (n=7) had lower leptin (P<0.05) but higher cortisol, interleukin-6, resting energy expenditure and fat oxidation than healthy subjects (n=6, P<0.05)." (PMID 15026790, 2004).
pancreatic cancer (continued). "If this were to be the case, then reduction of interleukin-6 concentrations would be a prerequisite for the reduction of insulin resistance and fat oxidation in weight-losing pancreatic cancer patients." (PMID 15026790, 2004). "Studies of weight-losing pancreatic cancer patients receiving high-purity EPA have demonstrated suppression of PBMC IL-6 production." (PMID 12966433, 2003). "Next, we used TCGA data to investigate whether IL6 expression levels in pancreatic tumors influence survival." (PMID 40523922, 2025). "However, the prevalence and clinical relevance of IL-6/GP130/JAK/STAT3 pathway activation in patients with pancreatic cancer remain poorly defined." (PMID 41397158, 2025). "In contrast to cancers such as colorectal or pancreatic cancer, where IL-6 facilitates epithelial–mesenchymal transition and metastasis, its presence in penile cancer might indicate a reactive inflammatory response that lacks prognostic significance." (PMID 41465261, 2025). "Beyond the physical barrier, a recent study found that autophagy in CAFs promotes the “target loss” of CD274 through the IL6/USP14/CD274 signaling pathway, further contributing to the formation of an “immune desert” in pancreatic cancer, thereby enabling evasion from CD8+ T cell-mediated killing." (PMID 40733146, 2025). "Here, we demonstrated the importance of IL-6 for TGFβ-specific immunity in pancreatic cancer." (PMID 39653766, 2025). "Initially, we reviewed the clinical data of patients, conducted univariate analysis, and combined with literature research on prognostic factors of pancreatic cancer, finally including 11 biological indicators (IL-2, IL-4, IL-6, IL-17, IFN-γ, NLR, LDH, CEA, AFP, CA19-9, β2-MG)." (PMID 41384105, 2025). "Since fibroblasts are key IL-6 producers in pancreatic cancer, we investigated whether treatment with the TGFβ vaccine could increase IL-6 production in this population, driving the elevated IL-6 levels in TCM." (PMID 39653766, 2025). "In pancreatic cancer specimens, neutrophils tended to co-localize with IL-6-positive CAFs." (PMID 39904796, 2025). "These insights suggest that targeting the IL-6/GP130/JAK/STAT3 axis may offer a promising therapeutic strategy for pancreatic cancer." (PMID 41397158, 2025). "In conclusion, MCPIP1 inhibited the IL6/JAK/STAT3 axis in pancreatic tumors." (PMID 40874680, 2025). "In pancreatic cancer, IL-6 is critical for TGFβ-specific T cells to exert anti-tumor effects." (PMID 41476977, 2025). "From the earliest stages of pancreatic intraepithelial neoplasia to the invasion and metastasis of pancreatic cancer cells and the appearance of tumor cachexia, IL-6 drives oncogenic signal transduction pathways and immune escape that accelerate disease progression." (PMID 38828409, 2024). "IL-6, in turn, supports pancreatic cancer cell proliferation by down-regulating miR-455-5p." (PMID 39595551, 2024). "Thus, in vitro blocking of IL-6R signaling by TCZ showed pSTAT3 downregulation and inhibition of IL-6 expression in both pancreatic cancer cells and mesenchymal stem cells (MSCs)." (PMID 38715108, 2024). "Indeed, epigenetic activation of this super-enhancer, as judged by Assay for Transposase-Accessible Chromatin (ATAC) sequencing signals, correlated with IL-6 expression in patients with esophageal and pancreatic cancers." (PMID 39128004, 2024). "In line with this, we previously showed that pancreatic tumor organoids from cachectic and non-cachectic pancreatic cancer patients expressed variable levels of known cachexia-associated cytokines, including IL-6, TNF-α, IL-8, IL-1α, IL-1β, Mcp-1, and LIF." (PMID 38339292, 2024). "Furthermore, they play a crucial role in the pancreatic cancer environment by releasing factors like SDF-1, HGF, galectin-1, TGFβ, and IL-6, promoting pancreatic cancer progression." (PMID 39199647, 2024).